FAM120A (family with sequence similarity 120 member A)
Description:
Membrane-associated scaffold protein that participates in multiple cellular processes, including oxidative stress-induced survival signaling, RNA trafficking and translational regulation, and the modulation of membrane signaling through its interaction with RNA-binding proteins and lipid raft-associated domains. Functions as a regulator of activation of several intracellular kinases, including SRC, FAK, and PI3K, following oxidative stress. Promotes RNA splicing and stability of lipogenic enzymes. Mechanistically, recruits the lipogenic transcription factor SREBP1 at active promoters, thereby bridging the newly transcribed lipogenic genes from RNA polymerase II to the SRSF1 and U1-70K-containing RNA-splicing machinery. Associates with key proteins of the NLRP3 inflammasome pathway and subsequently inhibits NLRP3 inflammasome activation. Sequesters a subset of AGO2-bound mRNAs from miRNA-mediated silencing by binding to poly(G)-rich motifs in their 3'-UTR independently of the AGO2 binding site, likely by preventing recruitment of miRISC effectors (By similarity).
Synonyms: C9orf10; KIAA0183; OSSA; HBVPTPAP
Tractability: Antibody: UniProt places it where antibodies can reach, with high confidence; its Gene Ontology location is reachable by antibodies, with medium confidence. PROTAC: ubiquitination databases record sites on it; its protein half-life has been measured.
Gene: Protein-coding gene on chromosome 9 (93,451,685 to 93,566,112, forward strand). Ensembl gene ENSG00000048828.
Subcellular location: Cytoplasm; Cell membrane
Subcellular location (Human Protein Atlas): Cytosol
Gene Ontology:
Molecular function: protein binding; protein-macromolecule adaptor activity; RNA binding
Biological process: negative regulation of NLRP3 inflammasome complex assembly; positive regulation of lipid biosynthetic process; positive regulation of RNA splicing
Cellular component: chromatin; cytoplasm; cytosol; membrane; plasma membrane; nucleus
Genetic constraint (gnomAD): Loss-of-function variants: 13 observed, 93.28 expected, observed/expected ratio (o/e) 0.14, 90% interval 0.09 to 0.22. The upper end of that interval is the gene's LOEUF score, 0.22, which puts it in group 1 of 6, group 1 being the genes least tolerant of losing a copy. Missense variants: 833 observed, 1,342.9 expected, observed/expected ratio (o/e) 0.62, 90% interval 0.58 to 0.66. Synonymous variants: 477 observed, 533.01 expected, observed/expected ratio (o/e) 0.89, 90% interval 0.83 to 0.96.
Homologues: Orthologues: macaque FAM120A (99% identical), guinea pig FAM120A (97% identical), rat Fam120a (97% identical), mouse Fam120a (96% identical), pig FAM120A (96% identical), dog FAM120A (95% identical), chimpanzee FAM120A (90% identical), rabbit FAM120A (83% identical), tropical clawed frog fam120a (77% identical), zebrafish fam120a (70% identical). Paralogues in human: FAM120C (54% identical), FAM120B (17% identical).
Diseases named in the same sentence as FAM120A in open-access papers:
FAM120A is named in the same sentence as 22 diseases in open-access papers, as found by Europe PMC text mining. Sharing a sentence is not in itself a finding about the gene and the disease. The quoted sentences say what the papers report.
colon cancer (5 papers, 2015 to 2025). "In colon cancer, they determined the scaffolding protein FAM120A to be an essential mediator of IL13/IL13RA2 signaling through FAK, PI3K and Src." (PMID 40663259, 2025). "Hsa_circ_104821 is derived from FAM120A (family with sequence similarity 120A), and its encoded protein is a signaling partner that activates the FAK and PI3K pathways in colon cancer metastasis." (PMID 28484086, 2017). "By a proteomic approach using colon cancer cells, we identified the proteins that co-immunoprecipitated with IL13Rα2 and found a scaffold protein, FAM120A, also known as C9orf10 or OSSA, as a major interactor." (PMID 26682245, 2015). "In summary, FAM120A is a scaffold protein required for the proper IL13Rα2-triggered signaling, which is involved in colon cancer metastasis." (PMID 26682245, 2015). "FAM120A was overexpressed in colorectal cancer cell lines and 55% of human colon cancer specimens." (PMID 26682245, 2015). "It has been also reported that IL-13Rα2 signaling requires a scaffold protein, FAM120A, to activate the FAK and PI3K pathways in colon cancer metastasis." (PMID 30165890, 2018).
gastric cancer (3 papers, 2020 to 2025). A primary or metastatic malignant neoplasm involving the stomach. "N6-methyladenosine modification of FAM120A enhanced cisplatin resistance by inhibiting ferroptosis and targeting FAM120A is an effective strategy to alleviate cisplatin resistance in gastric cancer." (PMID 38565940, 2024). "The overexpression of FAM120A significantly increases IGF-II protein in the culture medium in gastric cancer cells." (PMID 38565940, 2024). "FAM120A participates in the cytosolic transport of the mRNA and has been involved in the development of gastric cancer." (PMID 34968289, 2020). "In cisplatin-resistant gastric cancer (GC) tissues, upregulation of FAM120A expression was positively correlated with poor prognosis in GC patients." (PMID 40271153, 2025).
schizophrenia (3 papers, 2013 to 2025). A major psychotic disorder characterized by abnormalities in the perception or expression of reality. "One gene, FAM120A, was significantly associated with schizophrenia (p = 0.00064) after Bonferroni correction for testing 36 genes." (PMID 24050404, 2013). "The genes FAM120A, BTBD9, and RNF103 have not been previously linked to cancer; rather, they have been associated with schizophrenia, restless leg syndrome, and depression, respectively." (PMID 40608007, 2025).
Anxiety (2 papers, 2021 to 2022). Intense feelings of nervousness, tension, or panic often arise in response to interpersonal stresses. "Interestingly, the largest GWAS study identified six genetic susceptibility loci that were significantly associated with IBS, four of which were located in genes associated with mood and anxiety (NCAM1, CADM2, PHF2/FAM120A, DOCK9)." (PMID 36071849, 2022).
asthma (1 paper, 2025). "Notably, as the linear counterpart of circ-0001875, FAM120A is associated with inflammation or asthma." (PMID 40661956, 2025). "Interestingly, previous studies have shown that FAM120A, as the its linear counterpart of circ-0001875, is associated with inflammation or asthma." (PMID 40661956, 2025).
stomach adenocarcinoma (1 paper, 2024). "To uncover the function of FAM120A in GC, we first evaluated FAM120A levels by using the TCGA database and discovered an increase in FAM120A in stomach adenocarcinoma (STAD)." (PMID 38565940, 2024).
tumor (5 papers, 2020 to 2026). "Then, YTHDC1 enhanced the stability of FAM120A mRNA in an m6A-dependent manner, leading to the upregulation of FAM120A in resistant tumor cells." (PMID 38565940, 2024). "In summary, our study identified FAM120A as a tumor-promoting factor that plays an important role in promoting cisplatin resistance in GC by inhibiting ferroptosis." (PMID 38565940, 2024). "Tumors derived from FAM120A-depleted cells were consistently smaller and lighter than those formed by control GC cells, indicating that FAM120A depletion inhibited tumor growth in vivo." (PMID 38565940, 2024). "When compared to cisplatin therapy alone, the combination of FAM120A depletion with cisplatin significantly diminished the tumor growth index in GC, indicating that FAM120A depletion enhanced sensitivity to cisplatin in vivo." (PMID 38565940, 2024). "Upregulated FAM120A levels significantly correlated with tumor size (P = 0.01) and TNM stage (P = 0.001)." (PMID 38565940, 2024). "FAM120A depletion in combination with cisplatin therapy showed the strongest inhibition of tumor growth." (PMID 38565940, 2024). "The increased METTL3 expression in resistant tumor cells enhances the m6A modification of FAM120A mRNA." (PMID 38565940, 2024). "FAM120A expression was markedly elevated in cisplatin-resistant NSCLC cell lines and clinical tumor specimens and was essential for SG formation and cell survival following cisplatin-induced stress." (PMID 41328536, 2026). "Based on univariate analyses, tumor size (P = 0.024), TNM stage (P = 0.041) and FAM120A levels (P = 0.006) were correlated with the overall survival (OS) of GC patients." (PMID 38565940, 2024). "Upregulated genes were primarily associated with cell adhesion/invasion/metastasis (ELMO2, ADAM9, DLG1, TRPM7), metabolism/mitochondrial function (FAM120A, DARS2), and cellular transport/axonal trafficking (KIF1B, TBC1D5), indicating the presence of tumor microenvironment stress." (PMID 41404060, 2025). "We observed DHX9 and MATR3 (in Tumor A, set 1), HNRNPC and LARP1 (in Tumor A, set 2), SRSF1 (in Tumor B, set 1 & Tumor B, set 2), SRSF6 and IGF2BP2 (Tumor B, set 2), HNRNPU (in Tumor B, set 2 & Tumor C, set 2), and FAM120A and HNRNPA2B1 (in Tumor C, set 2)." (PMID 31892958, 2020). "Notably, FAM120A and GBE1 were significantly expressed in multiple cell types, suggesting their roles in CRC cell proliferation and providing new insights into their functions in tissue regeneration, inflammatory response, and tumor microenvironment regulation." (PMID 41049004, 2025).
cancer (4 papers, 2022 to 2025). A tumor composed of atypical neoplastic, often pleomorphic cells that invade other tissues. "Therefore, loss of Lamin A triggers nuclear AGO2 translocation, FAM120A mediated RNAi impairment, and upregulation of oncogenic miRNAs, facilitating cancer cell proliferation." (PMID 38994560, 2024).
FAM120A also shares sentences with these, for which no sentence is quoted: anxiety disorder (2 papers); depression (2); anorexia nervosa (1); autism (1); glioblastoma (1); hepatocellular carcinoma (1); male infertility (1); mood disorder (1); neuroblastoma (1); non-small cell lung carcinoma (1); Obesity (1); rectal tumor (1); restless leg syndrome (1); T-cell lymphoma (1).